COL9A3 (collagen type IX alpha 3 chain)
Diseases named in the same sentence as COL9A3 in open-access papers (continued):
Sharing a sentence is not in itself a finding about the gene and the disease.
osteochondrodysplasia (1 paper, 2020). A term referring to disorders characterized by abnormalities in the development of bones and cartilage. "One study performed candidate gene analysis for ACL rupture in the Newfoundland including COL9A3 as a candidate gene because of its known associations with primary arthritis and osteochondrodysplasias in humans." (PMID 33382735, 2020).
osteochondropathy (1 paper, 2015). "Extensive studies have provided evidence for the associations between the genes COL9A2, COL9A3 and osteochondropathy." (PMID 25774918, 2015).
renal carcinoma (1 paper, 2024). A carcinoma arising from the epithelium of the renal parenchyma or the renal pelvis. "The results of immunohistochemical analysis indicate that the expression levels of COL9A3, GPC4, and ITGA6 in renal cancer tissue are higher than those in normal tissue, whereas the expression levels of FREM2, ITGA9, and P3HI are lower than in normal tissue." (PMID 38365923, 2024).
seizure disorder (1 paper, 2014). "In the study, two of six patients had deletions that encompassed COL9A3 and one had seizure disorder, but they lacked in clinical features reminiscent of MED." (PMID 25381065, 2014).
Stickler syndrome, type 6 (1 paper, 2024). "COL9A3 variants cause Stickler syndrome type VI (OMIM 620022) characterized by hearing loss and skeletal abnormalities." (PMID 39701600, 2024).
X-linked adrenoleukodystrophy (1 paper, 2021). X-linked adrenoleukodystrophy (X-ALD) is a peroxisomal disorder resulting in cerebral demyelination, axonal dysfunction in the spinal cord leading to spastic paraplegia, adrenal insufficiency and in some cases testicular insufficiency. "In addition, in X-linked adrenoleukodystrophy patients, the combination of methylation levels of SPG20, UNC45A, and COL9A3 and also the expression levels of ID4 and MYRF would be a good marker for distinguishing the discriminating childhood from adult inflammatory phenotypes." (PMID 33691689, 2021).
tumor (10 papers, 2011 to 2025). "The present study is the first to show that abnormal COL9A3 expression is associated with the tumor size in NSCLC patients." (PMID 34855841, 2021). "Many signals favoring tumor cells were significantly activated in C2, such as integrin-related signals (COL9A3 − (ITGA2+ITGB1), JAM3 − (ITGAM+ITGB2), COL6A1 − (ITGA1+ITGB1)), immune suppression signals (CD99 − PILRA), etc.." (PMID 39391717, 2024). "Specifically, we observed the presence of copy number variants (CNVs) in 5q and 20q in addition to DEGs, such as COL9A3 and CRABP1, shared with other putative tumor clusters described further below." (PMID 35534852, 2022). "We also observed that higher expression of USP3 was associated with stronger expression of COL9A3 and COL6A5 in tumour tissues." (PMID 34930901, 2021). "As members of the collagen family, COL9A3 and COL6A5 serve as essential skeletons in the extracellular matrix (ECM), which is the major component of the tumour microenvironment." (PMID 34930901, 2021). "We collected tumour tissues and corresponding normal tissues of gastric mucosa from 12 GC patients and detected the expression of USP3, COL9A3, and COL6A5 by western blotting." (PMID 34930901, 2021). "In the five-gene signatures in the ceRNA network, the expression levels of DEPDC1, CPS1, COL9A3, and PTPN21 were significantly different between early- and advanced-stage tumor tissues." (PMID 34855841, 2021). "To further investigate the effects of the USP3-COL9A3/COL6A5 axis on tumour metastasis in GC in vivo, we established BGC-823 cells stably depleting USP3 by lentiviral transfection, with simultaneous overexpression of COL9A3 or COL6A5." (PMID 34930901, 2021). "Moreover, we further analysed USP3, COL9A3 and COL6A5 expression in tumour samples and adjacent normal tissues from 94 GC patients using TMA, along with their corresponding clinicopathologic information." (PMID 34930901, 2021).
cancer (7 papers, 2015 to 2024). A tumor composed of atypical neoplastic, often pleomorphic cells that invade other tissues. "The highest expression of genes encoding Col1a1-2, Col3a1, Col4a1, Col4a2, Col5a1, Col5a2, Col6a1, Col8a1, Col9a3, Col10a1, Col12a1, Col14a1, Col15a1, Col16a1, Col18a1, and Col28a1 were detected in untreated tumors, whose landscapes were dominated by Krt8+ cancer cells." (PMID 39372930, 2024). "Of which, the top 20 differential expressed genes (DEGs) were mainly related to the progression of malignant tumors, including SYT12, CLDN10, COL9A3, SFRP1, MT1G, MTIH, etc.." (PMID 36253446, 2022). "Semi-quantitative scoring showed that USP3, COL9A3 and COL6A5 proteins were expressed at significantly higher levels in cancer tissues than in adjacent normal tissues." (PMID 34930901, 2021). "The genes COL9A3, INPP5A and CYP2E1 were found in the regions with most frequently occurring homozygous deletions in each of the groups of hyperplasias, benign and malignant tumours." (PMID 25955013, 2015). "All these genes (AP2M1, FKBP11, GALNT6, BDNF, COL9A3 and NR4A1) favor relevant features of cancer progression, indicating that their epigenetic activation in CTCs of CRC patients under treatment could be a key event for the development of therapy resistance and cancer progression." (PMID 38188020, 2023). "However, there are few reports on the relationship between COL9A3/COL6A5 and cancer." (PMID 34930901, 2021).
myopathy (4 papers, 2010 to 2025). A disease of the muscle in which the muscle fibers do not function properly. "MED-causing COL9A3 exon-skipping mutations were first found to be associated with a mild myopathy phenotype, characterised by proximal muscle weakness and mild to moderate elevations in serum creatine kinase (CK) levels, which is a marker of muscle damage." (PMID 41155349, 2025). "MED has been associated with mild myopathy in some families, in particular one family with a COL9A3 mutation and two families with C-terminal COMP mutations." (PMID 20358595, 2010). "MED-related myopathy has been reported in some families with COL9A3, COMP, and COL9A2 mutations." (PMID 25381065, 2014). "Data analysis revealed the presence of a likely pathogenic missense variant in COL9A3 (NM_001853.4), a gene causative of epiphyseal dysplasia, type 3, with or without myopathy (MIM#: 600969, ORPHA: 166002) with an autosomal dominant pattern of inheritance." (PMID 35052694, 2021). "Furthermore, like COL9A3 mutations, myopathy is not a consistent feature of MED caused by COL9A2 mutations." (PMID 20358595, 2010).
skeletal dysplasia (2 papers, 2009 to 2019). Any Mendelian diseases that affects growth and development of the skeleton. "Some of these newly identified genes are well characterized as cartilage-selective and associated with one of a variety of forms of skeletal dysplasia (e.g., TRPV4, COL2A1, COMP, and COL9A3)." (PMID 20046828, 2009).
COL9A3 also shares sentences with these, for which no sentence is quoted: infection (2 papers); pseudoachondroplasia (2); achromatopsia (1); Arthritis (1); cerebral palsy (1); congenital stationary night blindness (1); connective tissue disorder (1); esophageal squamous cell carcinoma (1); fibrosis (1); glioblastoma (1); glioma (1); Hearing impairment (1); intervertebral discs degeneration (1); Leber congenital amaurosis (1); liver fibrosis (1); lung carcinoma (1); lymph node metastasis (1); lymphoma (1); muscular atrophy (1); neurodegenerative disease (1); rectal cancer (1); retinitis pigmentosa (1); Scheuermann’s kyphosis (1); scoliosis (1); Stroke (1); Ullrich congenital muscular dystrophy (1); Usher syndrome (1); Vitreoretinopathy (1).